CRP (C-reactive protein)
Diseases named in the same sentence as CRP in open-access papers (continued):
Sharing a sentence is not in itself a finding about the gene and the disease.
uremia (27 papers, 2008 to 2025). A clinical syndrome associated with the retention of renal waste products or uremic toxins in the blood. "Hence, we concluded plasma factors (uremia, CRP, globulins etc.)cause rouleaux formation to occur faster than it does in the control group, which is a risk factor for microcirculation." (PMID 28158274, 2017). "We found a positive correlation between reactive hyperemia index with systolic blood pressure (rho=0.753 p=0.0002), mean blood pressure (rho=0.660 p=0.002), high sensitive c-reactive protein (rho=0.486 p=0.035) and the uremia (rho=0.476 p=0.039)." (PMID 40519808, 2025). "After Spearman correlation tests, a positive correlation was found between reactive hyperemic index and systolic blood pressure (rho=0.753 p=0.0002), mean blood pressure (rho= 0.660 p= 0.002), hs-CRP (rho= 0.486 p= 0.035) and uremia (rho= 0.476 p= 0.039)." (PMID 40519808, 2025). "PMet newborn presented increase in uremia and CRP and significant rise of active MMP-2 and MMP-9 forms." (PMID 28133545, 2017). "Initial biological screening showed a platelet count at 153,000 cells/mm3, low creatinine clearance at 51 mL/min, high uremia at 13 mmol/L (normal <3.2), and C-reactive protein (CRP) at 94 mg/L (normal <3.2)." (PMID 23533431, 2013). "Another study also showed that HD patients with UP had significantly higher serum CRP and IL-6 levels compared to HD patients without UP, UP seems to be associated with an up-regulation of micro-inflammation in uremia." (PMID 33471852, 2021). "Those who are continuously undergoing high throughput blood purification have decreased serum levels of CRP, interleukin-2, and tumor necrosis factor-α, and high throughput hemodialysis may be beneficial for the prevention of infections in patients with uremia." (PMID 30818331, 2019). "Our study detect an inverse association of dialysis adequacy with both serum CRP and Ca×PO4 product, indicates that an adequate hemodialysis on one hand will be associated with lower Ca×PO4 product and on the other hand diminishes the inflammatory state of uremia." (PMID 25340109, 2012). "Moreover, C- reactive protein was also as a biomarker for inflammation in uremia." (PMID 18795103, 2008). "The substantial positive correlation between PCS and CRP was likely to represent a vicious cycle, with PCS accumulating systemic inflammation, and the preexisting inflammatory state of uremia amplifying the vasculotoxic effects of PCS." (PMID 41008726, 2025). "The increased levels of uremia, uricemia, ALT, total proteins, and C-reactive protein (CRP) in positive patients with typhoid fever were higher than in those with paratyphoid fever." (PMID 37461754, 2023). "Traditional inflammatory biomarkers, including CRP, TNF-α, and IL-6, have been found to be predictors of cardiovascular disease and even uremia." (PMID 31427482, 2019). "One study found that patients with uremia had elevated IL-6, TNF-α, and CRP levels." (PMID 34678995, 2021). "Biochemical parameters of newborn do not seem to be affected by Met enriched diet except for the uremia, which quadruples values, and CRP that increases very significantly (p < 0.0001)." (PMID 28133545, 2017). "However, the mean values of creatininemia, uremia, albuminemia, ALP, total bilirubin, conjugated bilirubin, AST, triglycerides, total protein, C-reactive protein (in both S. Typhi and Paratyphi positive patients) and ALT (in solely S. Typhi positive patients) were out of the normal ranges." (PMID 37461754, 2023). "Compared with uremia patients without skin pruritus, patients with UP had higher levels of IPTH, Hb, BUN, nPCR and hs-CRP." (PMID 33471852, 2021).
cardiomyopathy (26 papers, 2006 to 2025). A disease of the heart muscle or myocardium proper. "Acutely ill cardiac patients with underlying cardiomyopathy exhibit significantly elevated NT-proBNP levels, accompanied by only mildly elevated hs-Troponin I and CRP levels." (PMID 40141814, 2025). "To investigate potential associations between CRP values lower than the cut-off point and gender, etiology of cardiomyopathy, and CRT before transplantation, we used contingency tables and the Chi2 test with Yates’s correction, as well as Fisher’s exact test." (PMID 39685924, 2024). "CRP is a well-known inflammatory marker of several cardiovascular diseases, including cardiomyopathy." (PMID 35535358, 2022). "A study of 49 patients treated with trastuzumab demonstrated a high correlation between high sensitivity-CRP (hs-CRP) and the subsequent development of cardiomyopathy." (PMID 29534446, 2018). "GLP-1 RAs, especially semaglutide and tirzepatide, consistently reduced weight, inflammation (C-reactive protein), and myocardial stress (N-terminal pro B-type natriuretic peptide) while improving 6-min walk distance and Kansas City Cardiomyopathy Questionnaire scores, uniformly across BMI groups." (PMID 40978810, 2025). "In addition, P. bivia and P. timonensis showed positive correlation with ferritin, CRP, and D-dimer levels, as well as cardiomyopathy and respiratory rates." (PMID 39963971, 2025). "The most prominent gene pathway was diabetic cardiomyopathy, fitting previous reports of ventricular hypertrophy, impaired diastolic function, and cardiomyopathy in GK rats that may be mediated by CRP." (PMID 35677049, 2022). "In addition, the other two biomarkers related to the highest severity, H. parainfluenzae and P. dentalis, also showed a positive association with CRP, D-dimer, and cardiomyopathy, even though it was not statistically significant (R = 0.2)." (PMID 39963971, 2025). "In two studies performed on norepinephrine-induced cardiomyopathy and HF models in rats, it was found that RDN can inhibit transforming growth factor-β1, MMP2, collagen I, and inflammatory cytokines CRP and TNF-α." (PMID 36035484, 2022). "Although EAT thickening could be related to other cardiomyopathies such as ischemic cardiac disease, an enlargement of EAT has been observed by 2D-Echo-Döppler in both T1DM and T2DM patients in correlation with HF and cardiac biomarkers (i.e., BNP, troponin-T and C-reactive protein)." (PMID 28231848, 2017).
encephalitis (26 papers, 2010 to 2026). An acute inflammatory process affecting the brain parenchyma. "The neurological manifestations of the patient are associated with high serum levels of the C-reactive protein and with the neutrophils count, a decreasing number of lymphocytes being a severe prognosis marker in the evolution of encephalitis in children associated with coronavirus infections." (PMID 32756188, 2020). "Statistical analysis revealed that advanced age, elevated CRP levels, increased d‐dimer levels, and high viral load were significantly associated with the occurrence of SFTS‐associated encephalitis." (PMID 39660909, 2024). "C-reactive protein (CRP) levels were measured for 26 out of 97 encephalitis cases (27%) and were mostly normal with a median value of 1 mg/L (IQR 24 mg/L)." (PMID 38137968, 2023). "The peripheral white blood cell count and C-reactive protein (CRP) were elevated at presentation, while head computed tomographic (CT) and cerebrospinal fluid (CSF) investigations, including an encephalitis panel, were normal." (PMID 35352986, 2022). "CRP levels from the anti-NMDAR encephalitis patients were significantly higher than healthy controls and significantly reduced after treatment." (PMID 35031011, 2022). "Thus, elevated circulating levels of CRP may be associated with the severity and poor prognosis of anti-NMDAR encephalitis in patients and also an increased risk of SE." (PMID 35031011, 2022). "C-reactive protein (CRP) and procalcitonin (PCT) in encephalitis/encephalopathy group were both slightly increased, which was statistically different from that in the non- encephalitis/encephalopathy group (p < 0.05)." (PMID 34479504, 2021). "An appropriate method for the diagnosis of neuroinflammation in vivo using blood examination (e.g., measuring the C-reactive protein) is not available, including for cases of severe classical encephalitis, which require neuroimaging and CSF examination." (PMID 32973573, 2020). "On the other hand, despite four patients with non-viral cause of encephalitis, the median levels of inflammation markers like ESR, leucocytes, neutrophils, CRP and D-dimer were significantly lower in patients with encephalitis." (PMID 30669985, 2019). "None of the clinical pictures were suggestive for viral encephalitis, as evidenced by apyrexia, normal CRP, negative molecular virological screening on plasma, non suggestive MRI and EEG pictures." (PMID 20181110, 2010). "Although acute-phase reactants such as CRP and procalcitonin are increasingly used to identify infections, we could not find significantly higher levels of serum CRP and procalcitonin in virus-positive compared with virus-negative encephalitis cases." (PMID 29170534, 2017). "Our study demonstrated that most of our patients diagnosed with autoimmune rather than infectious‐nonbacterial encephalitis presented without evidence of fever, had normal CSF WBC and protein, and normal serum ESR and CRP." (PMID 35713518, 2022).
Headache (26 papers, 2015 to 2025). Cephalgia, or pain sensed in various parts of the head, not confined to the area of distribution of any nerve. "It is well known that higher CRP is related to decreased pain threshold and is implicated in the inflammatory process of various types of headache." (PMID 33146038, 2020). "Furthermore, persistent inflammatory activity might contribute to disease progression and headache chronification, a hypothesis supported by the weak but statistically significant association between hs-CRP levels and MHDs." (PMID 41402545, 2025). "The work-up for hypnic headache includes a brain MRI, erythrocyte sedimentation rate, C-reactive protein, polysomnography, and 24-hour blood pressure monitoring." (PMID 39925537, 2025). "Another research reported findings of decreased IL-1β and elevated IL-6 levels during headache attacks and also demonstrated that IL-1β had the highest discriminative value between patients with headaches and controls compared to CRP and IL-6." (PMID 37176049, 2023). "We used the optimal cut-off for CRP or PCT combined with headache or rhinorrhea to discriminate viral from bacterial LRTIs." (PMID 34583675, 2021). "In this study, frequent symptoms of headache were associated with biomarkers of endothelium damage, such as high PCT and CRP levels." (PMID 33391152, 2020). "CRP, TNF-α and IL-6 have been positively associated with migraine headache, a usual symptom of PMS22." (PMID 31624297, 2019). "In addition, several indicators that reflect the health status of the body, such as lipid levels, C-reactive protein (CRP), and blood pressure, have also been demonstrated by previous studies to have an impact on headache." (PMID 36686472, 2022). "Furthermore, abnormal CRP values as marker for infections were also more common within the secondary headache group." (PMID 29285572, 2017). "In this study, for example, the PCA showed that CRP and PCT levels followed simultaneous changes in relationship with diverse headache features." (PMID 33391152, 2020). "Compared to those without headache, participants with headache tended to be girls and adolescents, have less calcium intake, and have higher levels of BMI, CRP, serum ferritin and TGs (all P < 0.05)." (PMID 36686472, 2022). "Further, CRP levels do not significantly differ based on headache frequency, headache intensity, preventive treatment, MO, and FM." (PMID 36313504, 2022). "Compared to those without headache, participants with headache tended to be girls and adolescents, have less calcium intake, and have higher levels of body mass index (BMI), C-reactive protein (CRP), serum ferritin and triglycerides (TGs) (all P < 0.05)." (PMID 36686472, 2022). "However, the n = 67 participants with headache at baseline had similar (mean ± SD) BMI, 28.08 ± 4.70 kg/m2, and median CRP, 1.52 mg/L, as the n = 127 without headache, 27.89 ± 4.58 kg/m2, and 1.53 mg/L." (PMID 34062937, 2021).
Immunodeficiency (26 papers, 2013 to 2026). Failure of the immune system to protect the body adequately from infection, due to the absence or insufficiency of some component process or substance. "Elevated CRP levels, palatal necrosis, immunodeficiency, and shorter antifungal therapy during hospitalization were associated with increased mortality, while use of posaconazole improved survival." (PMID 41280319, 2025). "Traditional host biomarkers such as C-reactive Protein (CRP) or procalcitonin (PCT) are of limited use in the setting of surgery induced inflammatory response, drug- or surgery-induced immunodeficiency, underlying malignancy or high levels of multimorbidity." (PMID 39576568, 2024). "Odds of complication in ECM-treated patients demonstrated greater sensitivity to T vs B cell phenotypes, with T cell immunodeficiencies being associated with lower odds of fever, ESR/CRP elevation, dehiscence, bleeding, mortality, tissue ischemia, and hematoma." (PMID 41001471, 2025). "Our findings indicate that more severe immunodeficiency and higher mycobacterial antigen load (extra-pulmonary disease and shorter interval between ATT and ART initiation) along with higher levels of IL-6 and CRP prior to ART initiation are strongly associated with paradoxical TB-IRIS." (PMID 23691062, 2013). "Included were patients with confirmed innate or intrinsic immunodeficiencies based on CBC, CRP, immunoglobulin levels, lymphocyte subpopulations, and whole-exome sequencing." (PMID 41209815, 2025). "Inability to mount a CRP response could be explained by low CD4 count of 127 ± 99 μl/ml in their study as compared to 520 ± 236 μl/ml in the current study, as severe immunodeficiency (< 50 μl/ml) is reported to significantly limit inflammatory response, in addition to an increased risk of death." (PMID 31331321, 2019).
infective endocarditis (26 papers, 2007 to 2025). Infective endocarditis (IE) is an infection of the inner lining of the heart chambers (endocardium) and valves. "A CRP of more than 720 mg/L can predict high-risk individuals with a high in-hospital mortality rate due to infective endocarditis." (PMID 37873776, 2023). "Our previous reports on patients treated for infective endocarditis in our hospital from 1980 onwards have focused on diagnostic classification, neurological manifestations, and the utility of the serum C-reactive protein (CRP) in assessing the outcome of the disease." (PMID 17640339, 2007). "The patient’s presentation was atypical for ME, with fever and laboratory findings of neutrophilia and elevated CRP features more suggestive of infective endocarditis." (PMID 41018352, 2025). "Serial CRP measurements are valuable in infective endocarditis as they allow us to monitor disease activity over time." (PMID 39499433, 2024). "Glasgow prognosis score, determined using albumin and C-reactive protein levels, is a simple and practical index for predicting the prognosis of patients hospitalized with infective endocarditis." (PMID 38656008, 2024). "This study aimed to evaluate the accuracy and prognostic value of the sequential organ failure assessment (SOFA) score combined with C-reactive protein (CRP) in patients with complicated infective endocarditis (IE)." (PMID 33869237, 2021). "For example, CRP concentrations are commonly used to support diagnosis of infective endocarditis and to monitor patient response to therapy." (PMID 28264059, 2017). "Aim of this study was to evaluate the prognostic value of PCT in comparison to white blood cell count (WBC) and C-reactive protein (CRP) for clinical outcome and its correlation with microbiological etiology in patients with infective endocarditis (IE)." (PMID 23767848, 2013). "In contrast to previous retrospective studies with smaller sample sizes, the current study reports a significantly higher admission level of CRP and lower level of haemoglobin in patients with concomitant spondylodiscitis when compared with patients with infective endocarditis alone." (PMID 39499433, 2024). "Similarly, earlier detection of infective endocarditis or intracardiac thrombosis could be supported by patient and primary care education with community-based CRP and blood cultures or D-dimer measurements and enabling direct referral pathways." (PMID 35407666, 2022). "A diagnosis of infective endocarditis was further supported by his chronic night sweats, fevers, and elevated inflammatory markers (ESR and CRP)." (PMID 27895947, 2016). "On arrival to hospital, patients with infective endocarditis and concomitant spondylodiscitis had a significantly higher CRP level compared with patients without spondylodiscitis (173.9 ± 109.4 vs 116.8 ± 87.9, p = 0.004)." (PMID 39499433, 2024). "Since fever is a common symptom in IVLBCL as well as elevated C-reactive protein, an echocardiogram may be necessary to rule out infective endocarditis." (PMID 40423224, 2025). "According to studies, there are several characteristics that increase the likelihood of embolization in infective endocarditis, including the vegetation’s size (> 10mm), motility, location on the mitral valve as opposed to the aortic valve, and a CRP level of > 40mg/l." (PMID 38340179, 2024). "The present study was aimed at evaluating the predictive value of combined CRP and RDW for outcomes of patients with blood culture-negative infective endocarditis (BCNE)." (PMID 29050353, 2017).